MTOR (mechanistic target of rapamycin kinase)
Diseases named in the same sentence as MTOR in open-access papers (continued):
Sharing a sentence is not in itself a finding about the gene and the disease.
cancer (continued). "It is suggested that ROS/AKT/mTOR could play an important role in neoneurogenesis and could be a potential target for antipsychotic drugs for cancer treatment." (PMID 37566075, 2023). "In addition, silibinin, a major bioactive component of silymarin, exhibits anti-angiogenic and anti-proliferative effects in various human cancer models and inhibits the mTOR signaling pathway in human cervical and hepatoma cancer cells." (PMID 37762688, 2023). "These pathways, including tight junction, transcriptional dysregulation in cancer, cancer-associated pathways, cell cycle, regulation of actin cytoskeleton and others, are also closely associated with the PI3K-Akt-mTOR/Erk-MAPK cascades and are important for angiogenesis 38-44." (PMID 37153740, 2023). "The same approach may maximize the effect of PD-1 blockade and mTOR inhibitors for cancer treatments." (PMID 36378537, 2023). "Therefore, the current study tries to identify a phytochemical with dual specificity for both PI3K and mTOR, which can be an effective molecule in the treatment of cancer." (PMID 36244040, 2023). "Moreover, clinically, the PTEN mutational status affects the response to combined therapy based on MEK and mTOR inhibitors in cancer; this should be taken into consideration when looking at individualized RB therapies in the future." (PMID 37965463, 2023). "Likewise, APOE is said to play a role in the activation of several cell pathways associated with cancer progression, including ferroptosis, apoptosis, DNA damage response, and intracellular signaling pathways such as PI3K/AKT, RTK, and TSC/mTOR." (PMID 38067270, 2023). "One of the most frequently altered signaling pathways in cancer is the PI3K/Akt/mTOR pathway." (PMID 36851737, 2023). "In conclusion, the downregulation and kinase activity of PDHA1 may function with the PI3K-Akt-mTOR pathway in some way, which could suppress the cuproptosis level and account for the cancer-like pathology in EMs." (PMID 36474131, 2023). "The mTOR pathway has a vital role in the maintenance of cell growth, proliferation, motility, and survival that is involved in the development of a variety of cancers." (PMID 37198626, 2023). "The PI3K/AKT/mTOR signaling pathway has been shown to be deregulated in a wide range of cancers." (PMID 36768370, 2023). "Genetic alterations in mTOR signaling have been implicated in metabolic disorders, neurodegeneration, ageing and in various cancer types; in particular, dysregulations of mTOR pathway have been detected in 36% of patients with SCLC and have been related to radiation and chemotherapy resistance." (PMID 36765949, 2023). "Thus, our study provides an unexpected model for controlling mTOR overactivation through pharmacological VC treatment and offers a potential therapeutic method for cancer treatment." (PMID 36787291, 2023). "mTOR is frequently upregulated in cancers, and mTOR overexpression could also block the mPTP opening to the same extent as activating AKT and inactivating GSK3β." (PMID 36982637, 2023). "Therefore, recent advances in research on mTOR inhibition involve various compounds developed to disrupt the metabolic process of cancer cells through the PI3K/AKT/mTOR pathway." (PMID 38057772, 2023). "The PI3K/Akt/mTOR pathway dual inhibitors have exhibited a promising therapeutic effect in cancer." (PMID 37730663, 2023). "The activation of AMPK is followed by serine/threonine‐protein kinase mTOR (mTOR) inhibition leading to favourable phenotypic outcomes in cancer cells, such as reducing protein synthesis and proliferation rates, activation of autophagy and inhibition of inflammatory responses." (PMID 36781298, 2023). "Considering that the inhibition of mTOR could inhibit tumor growth, we explored whether the induction of mTORC1 inactivation could function as a potential therapeutic method for cancer treatment." (PMID 36787291, 2023).
cancer (continued). "In addition to some already identified pro-cancer downstream molecules, the activation of mTOR signalling was found to promote DNA methylation by increasing the translation of DNMT1." (PMID 37088830, 2023). "Because the effect of mTOR targeting is largely cytostatic, the utility of mTOR inhibitors as single agents for cancer treatment may be limited." (PMID 38203186, 2023). "Bioinformatic analyses using IPA and ROMA software revealed significant up-regulation of multiple signaling pathways previously linked to cancer cells and their stromal microenvironment, including the three major MAPKs (ERK, JNK, p38), the PI3K/AKT/mTOR and integrin/ILK/actin cytoskeleton." (PMID 37696912, 2023). "The increase in LAT1 expression in cancer cells facilitates the influx of amino acids, which can aid in the regulation of several signaling pathways and induce the activation of the mechanistic target of rapamycin (mTOR) kinase, an important nutrient sensor that facilitates tumor proliferation." (PMID 37298344, 2023). "Another study has shown that the inhibition of PNCK might delay proliferation and accelerate apoptosis in cancer cells by regulating the PI3K/AKT/mTOR signaling pathway." (PMID 36645171, 2023). "Although not fully understood, it is hypothesized that the major driving mechanism of metformin’s anti-cancer activity is likely related to the inhibition of the mammalian target of rapamycin (mTOR) pathway." (PMID 37760509, 2023). "In addition, aberrant activation of the PI3K/AKT/mTOR signaling pathway is frequently found in a variety of cancers." (PMID 36959811, 2023). "Several miRNAs modulate necroptosis is cancer cells with the involvement of mTOR and HIF1A." (PMID 36835100, 2023). "Our study provides a new insight to the mechanism of Akt/mTOR signaling pathway, suggesting that selective Akt/mTOR signaling pathway inhibitors may help to overcome drug resistance and improve the efficacy of anti-cancer treatment." (PMID 36900050, 2023). "PI3K/AKT/mTOR pathway plays a vital function in diseases and cancers." (PMID 36988258, 2023). "The pathway that is frequently activated in most cancer cases is the PI3K/Akt/mTOR pathway." (PMID 36244040, 2023). "Additionally, many clinical trials based on second-generation mTOR inhibitors for cancer therapy are ongoing." (PMID 37088830, 2023). "It has been reported that many PI3K/Akt/mTOR small molecule inhibitors are widely used in preclinical studies, and some inhibitors, such as idelalisib, duvelisib and deforolimus, have been clinically approved for cancer treatment." (PMID 37608281, 2023). "This suggests CVM-1118 may have the potential to treat cancer patients carrying STK11- or NF2-deficient mutation–via targeting TRAP1 and inhibiting the activation of mTOR/AKT signaling pathways." (PMID 37351538, 2023). "It has been reported that voxtalisib could suppress the phosphorylation of PI3K and control the incorporation of mTOR effector in cancer cells." (PMID 37046703, 2023). "Silibinin inhibits the mTOR signaling pathway in various cancer cell lines." (PMID 37762688, 2023). "Therefore, our study provides a rationale to explore the potential therapeutic outcome of NUAK1 inhibition and additional combinations with Akt or mTOR inhibitors in several types of cancer." (PMID 38135881, 2023). "Inhibitors of mTOR have been approved for the treatment of various cancers." (PMID 38041544, 2023). "mTOR involves two distinct complexes, mTORC1 and mTORC2, that participate in response to growth factors, but generally hyperactivation of the mTORC1 is involved in the regulation of cell proliferation and progression of cancer." (PMID 37511619, 2023). "It is well known that UroA inhibits AKT and mTOR while upregulating PTEN in many cancer types." (PMID 36937838, 2023). "Targeting the PI3K/mTOR pathway therefore may be particularly effective in cancers that signal through PI3Ka." (PMID 38025526, 2023).
cancer (continued). "The PI3K/mTOR pathway has a major effect on the regulation of processes such as autophagy, proliferation and apoptosis, which sequentially affects the occurrence and development of cancer." (PMID 36768253, 2023). "However, both the Th and the cancer cells use glycolysis for energy, and the PI3k/Akt/mTOR axis is suppressed." (PMID 36982245, 2023). "Thus, various studies have demonstrated that the inhibition of PI3K-Akt-mTOR signaling is a prospective therapeutic strategy for cancer [15, -17]." (PMID 36864505, 2023). "In general, cancer cells are frequently confronted with energy stress due to their rapid growth and limited oxygen supply, which inhibits the activity of mTOR signaling and potentially weakens the regulatory role of the BRD4-SRPK2-SRSF2 axis on ACSL3 expression." (PMID 37993451, 2023). "In addition, cyclin D-CDK4/6 activity is controlled by mitogenic pathways, such as PI3K and mTOR, which are also frequently deregulated in cancer and are abnormally elevated in AVM ECs 20,29,35." (PMID 37745444, 2023). "Pathways in cancer includes cell cycle components, mTOR and transcription factors." (PMID 36720985, 2023). "The mammalian target of rapamycin (mTOR) is often activated in several cancers." (PMID 36768934, 2023). "Rapamycin has been reported to limit the growth of cancer cells by suppressing mTOR." (PMID 37204251, 2023). "In fact, targeting mTOR to treat cancer is also confusing in some ways." (PMID 37049920, 2023). "Furthermore, nimbolide induces cancer cell autophagy by inhibiting mammalian target of rapamycin (mTOR) and p62 expression and increasing two essential proteins, Beclin 1, and LC3B expression." (PMID 37132286, 2023). "The frequent hyperactivation of the mTOR pathway makes it a promising target for cancer therapy." (PMID 37088830, 2023). "mTOR is a regulator associated with autophagy, and saponins reportedly target autophagy through the AMPK/mTOR signaling pathway to slow the malignant progression of cancer." (PMID 37063281, 2023). "Hence, EGCG exerts its anti-cancer properties by targeting a range of signaling pathways, particularly the PI3K/AKT/mTOR pathway, which is responsible for uncontrolled cancer cell proliferation and metastasis." (PMID 36765820, 2023). "In this context, our study is meticulously designed to elucidate the conjoint action of curcumin and plumbagin in targeting the PI3K/Akt/mTOR cascade, a discovery that could herald significant strides in cancer therapy." (PMID 38239204, 2023). "Summary of the mTOR-based drug combinations investigated in various cancers." (PMID 37513916, 2023). "The mTOR activation mechanism in human cancers is the epigenetic and genetic alteration of the upstream signaling molecules, methylation of PTEN, mutations of Ras, PIK3CA, and PTEN, and the genetic copy gain of receptor tyrosine kinase genes and other genes in the MAP kinase and PI3K/Akt pathways." (PMID 36980552, 2023). "Rapamycin, a specific inhibitor of mTOR that is a central regulator of metabolism and cell growth, has been extensively demonstrated to be useful in the treatment of various diseases, including cancer." (PMID 37063610, 2023). "Moreover, it regulates various functions in gastric, prostate, and thyroid CSC lines via the mammalian target of rapamycin (mTOR) pathway, blocking cell growth and metastasis and the progression of cancer cell apoptosis and autophagy." (PMID 37046789, 2023). "The PI3K/AKT/mTOR pathway is crucial to cancer cell proliferation, migration, and invasion." (PMID 36898991, 2023). "We found that TFRC knockdown inhibited cancer progression via the PI3K/Akt/mTOR signaling pathway." (PMID 37644594, 2023).
cancer (continued). "The pattern of co-mutation of cancer-related genes varied among carcinomas and the groups, with group 1 showing a low frequency of co-mutated genes in all carcinomas and groups 2 and 3 showing varying degrees of mutations in MAPK and PI3K/MTOR pathway genes downstream to ERBB2." (PMID 37754252, 2023). "Additionally, lanatoside C, a natural antiarrhythmic product derived from Digitalis lanata, shows antiproliferation, apoptosis, and DNA damage in cancer cells by inactivating PI3K/AKT/mTOR." (PMID 36139919, 2022). "Analogous to its role in regulating physiological diapause, mTOR inhibition may induce a reversibly paused state in cancer cells, leading to drug tolerance and chemoresistance." (PMID 36396656, 2022). "Mechanistic target of rapamycin (mTOR), a serine/threonine protein kinase that is ubiquitously expressed in mammalian cancer, is classified into two complexes, mTOR complex 1 (mTORC1) and mTOR complex 2 (mTORC2), and these complexes have distinct roles in cells." (PMID 35955892, 2022). "Similarly, high expression of the PI3K/AKT/mTOR signalling has been found in several cancers, especially in COAD." (PMID 35814224, 2022). "Deregulation of mTOR contributes to cancer progression and drug resistance." (PMID 35328346, 2022). "In contrast, PI3K and mTOR inactivations induce ferroptosis in cancer cells." (PMID 36139919, 2022). "Rictor and mTOR are prevalently observed in cancer, while mutations in mSin1, mLST8 and Raptor are not common in human cancers." (PMID 36539659, 2022). "mTOR-mediated translation initiation is augmented in many cancers." (PMID 35805935, 2022). "Whether and how these GTPases regulate mTOR in senescent cells or senescence-like cancer cells remains poorly characterized." (PMID 36267578, 2022). "Indeed, mTOR signaling interacts with TME through programmed cancer cell death axis (PD-L1/PD1) that is stimulated by PTEN deletion or loss of function, as well as effects on T cell differentiation." (PMID 36139669, 2022). "However, mTOR inhibition in cancer, especially as a monotherapy, has limited advantages, extending lifespan by only a few months in certain trials, and other studies have shown the occurrence of drug resistance." (PMID 36293326, 2022). "Consequently, multiple candidate anticancer agents suppress tumor growth by inhibiting PI3K/Akt/mTOR pathways and then inducing autophagy, as well as apoptosis of cancer cells." (PMID 36287985, 2022). "We also found that combined administration of TEM and anti-PD-L1 increased the number and activity of CD8+ T cells and this is consistent with a recent report that mTOR inhibition and combination therapy with an immune checkpoint inhibitor can enhance the anti-cancer effect." (PMID 36077620, 2022). "The signaling pathway composed of PI3K, protein kinase B (AKT), and mTOR is a part of a complicated signaling cascade comprising distinct upstream regulators and downstream effectors, which play critical roles in the formation processes of human cancers." (PMID 36539659, 2022). "The KLHL22-CUL3 E3 ligase acts as a positive regulator of mTOR in cancer cells and in C. elegans." (PMID 36440598, 2022). "The PI3K/AKT/mTOR signaling pathway plays an important role in regulating the balance between cell proliferation, apoptosis and autophagy in response to cellular stress induced by chemotherapeutics in cancer cells." (PMID 35458629, 2022). "Deviance from the normal mTOR regulation has often been reported in cancer pathology." (PMID 35530256, 2022). "WES showed relevant mutations in several cancer-related genes, and the comparative mRNA expression analysis showed 36 differentially expressed genes associated with EGFR tyrosine kinase inhibitors resistance, RAS, MAPK, and mTOR signaling." (PMID 35011716, 2022). "However, primary tumors and distant metastases eventually acquired resistance after long-term treatment, despite continued effective suppression of mTOR signaling in cancer cells." (PMID 36539444, 2022).
cancer (continued). "As we all known, PI3K/AKT/mTOR is a typical cancer-promoting signaling pathway." (PMID 35706026, 2022). "Moreover, IGF-1 activates the Pi3k–Akt–mTor pathway, which helps to reprogramme metabolism in cancer." (PMID 35460513, 2022). "Next, we determined whether autophagy plays a key role in mTOR-mediated cancer stemness, using the autophagy inhibitor hydroxychloroquine (HCQ)." (PMID 35406578, 2022). "Further research found that the combination of MC-4 and everolimus can synergistically exert anticancer effects through AKT/PKM2 and mTOR to inhibit cancer growth and metastasis, which provides a theoretical basis for the combination of targeted therapy with glycolysis inhibitors." (PMID 36230492, 2022). "Since mTOR is at a nexus of cellular signaling networks that control the anabolic and catabolic processes inside every cell in the body, it makes this kinase an attractive target for therapies against diseases of altered metabolism such as cancer." (PMID 36388131, 2022). "In the current study, we tested the hypothesis that the pan-class I PI3K/mTOR antagonist bimiralisib would result in cancer cell apoptosis and concomitant tumor shrinkage in NOTCH1-mutant HNSCC." (PMID 36124629, 2022). "ROS activates PIK3/AKT/mTOR signaling in the pathogenesis of cancer." (PMID 36014933, 2022). "In addition, the silencing of some CPSFs has also been determined to inhibit cancer progression by inhibiting the PI3K/AKT/mTOR pathway, such as the CPSF3-PI3K/Akt/GSK-3β in HCC, CPSF4-PI3K/AKT in LUAD, and CPSF7-PTEN/AKT in HCC." (PMID 36349192, 2022). "Several anti-cancer drugs activate autophagy by inhibiting the PI3K/Akt/mTOR pathway." (PMID 36180880, 2022). "Originally, ATP-binding mTOR inhibitors were developed to treat cancer." (PMID 36561137, 2022). "In addition, PI3K/AKT/mTOR signaling pathway is one of the most frequently activated pathway in various human cancers and plays a crucial role in promoting tumor initiation and progression." (PMID 35458629, 2022). "mTOR is a key node in the TGF-β signaling pathway to enhance cancer stemness and drug resistance." (PMID 35558559, 2022). "Another gene, the La-related protein 1 (LARP1), has been shown to interact with 3000 mRNAs linked to cancer pathways, including post-transcriptionally controlled mTOR which was frequently dysregulated in cancer, promoting cell motility, invasion, and anchorage-independent growth." (PMID 35982949, 2022). "Although the MTOR gene and its partners in the mTOR signaling pathway were selected for their roles in the development, proliferation and migration of cancer cells, any other subset of genes would confirm the independence of the AVE, REV and COR characteristics." (PMID 35723406, 2022). "We investigated whether the inhibitory effect of 3039-0164 on PRMT5 affected the activation of the AKT, ERK, and mTOR signaling pathways to learn more about the mechanism of cancer inhibition and the inhibitory effect of 3039-0164." (PMID 36364261, 2022). "Furthermore, the mammalian target of the rapamycin (mTOR) signaling system is involved in many aspects of cancer such as cell growth, the inhibition of apoptosis, and metabolic reprogramming proliferation." (PMID 35745580, 2022). "Indeed, the mTOR axis promotes the generation of soluble components important in MDSC recruitment in cancer cells, whereas mTOR signaling modulates the expression of a particular antigen on the surface of MDSCs." (PMID 36428613, 2022). "In addition, azithromycin suppressed mammalian target of rapamycin (mTOR), which is frequently activated in cancer cells." (PMID 35159037, 2022). "In addition, this review summarizes the literature relating to the potential combination of mTOR inhibitors with several therapies for the management of various forms of cancer." (PMID 36428613, 2022). "Therefore, downregulation of the PI3K/AKT/mTOR pathway is generally suggested as a therapeutic target for cancer diseases." (PMID 35052675, 2022).